RBM15B (RNA binding motif protein 15B)
Description:
RNA-binding protein that acts as a key regulator of N6-methyladenosine (m6A) methylation of RNAs, thereby regulating different processes, such as alternative splicing of mRNAs and X chromosome inactivation mediated by Xist RNA. Associated component of the WMM complex, a complex that mediates N6-methyladenosine (m6A) methylation of RNAs, a modification that plays a role in the efficiency of mRNA splicing and RNA processing. Plays a key role in m6A methylation, possibly by binding target RNAs and recruiting the WMM complex. Involved in random X inactivation mediated by Xist RNA: acts by binding Xist RNA and recruiting the WMM complex, which mediates m6A methylation, leading to target YTHDC1 reader on Xist RNA and promoting transcription repression activity of Xist. Functions in the regulation of alternative or illicit splicing, possibly by regulating m6A methylation. Inhibits pre-mRNA splicing. Also functions as a mRNA export factor by acting as a cofactor for the nuclear export receptor NXF1.
Synonyms: HsOTT3; OTT3; HUMAGCGB
Tractability: PROTAC: UniProt records ubiquitination sites on it; ubiquitination databases record sites on it; its protein half-life has been measured.
Gene: Protein-coding gene on chromosome 3 (51,391,285 to 51,397,908, forward strand). Ensembl gene ENSG00000259956.
Subcellular location: Nucleus, nucleoplasm; Nucleus speckle; Nucleus envelope
Subcellular location (Human Protein Atlas): Nucleoplasm
Gene Ontology:
Molecular function: protein binding; RNA binding; mRNA binding; nucleic acid binding
Biological process: dosage compensation by inactivation of X chromosome; negative regulation of DNA-templated transcription; nucleocytoplasmic transport; regulation of alternative mRNA splicing, via spliceosome; RNA methylation; mRNA export from nucleus
Cellular component: nuclear envelope; nuclear speck; nucleolus; nucleoplasm; RNA N6-methyladenosine methyltransferase complex; nucleus
Genetic constraint (gnomAD): Loss-of-function variants: 11 observed, 46.24 expected, observed/expected ratio (o/e) 0.24, 90% interval 0.15 to 0.39. The synonymous counts are far from expectation, so gnomAD's model fits this gene poorly and the ratio says little. Missense variants: 1,136 observed, 1,159.8 expected, observed/expected ratio (o/e) 0.98, 90% interval 0.93 to 1.03. Synonymous variants: 631 observed, 506.06 expected, observed/expected ratio (o/e) 1.25, 90% interval 1.17 to 1.33.
Homologues: Orthologues: dog RBM15B (97% identical), pig RBM15B (97% identical), guinea pig RBM15B (96% identical), mouse Rbm15b (96% identical), rat Rbm15b (95% identical), zebrafish rbm15b (55% identical), macaque RBM15B (52% identical), tropical clawed frog rbm15b (48% identical), Drosophila melanogaster nito (30% identical), Drosophila melanogaster nonA (8% identical), Drosophila melanogaster nonA-l (7% identical). Paralogues in human: RBM15 (43% identical), SPEN (24% identical), RAVER1 (10% identical), SFPQ (9% identical), RAVER2 (8% identical), PSPC1 (8% identical), NONO (7% identical).
Diseases named in the same sentence as RBM15B in open-access papers:
RBM15B is named in the same sentence as 48 diseases in open-access papers, as found by Europe PMC text mining. Sharing a sentence is not in itself a finding about the gene and the disease. The quoted sentences say what the papers report.
glioma (6 papers, 2020 to 2023). A benign or malignant brain and spinal cord tumor that arises from glial cells (astrocytes, oligodendrocytes, ependymal cells). "We found that the protein expression of IGF2BP3 and RBM15B was increased in the glioma tissue, while the expression of RBM15 was decreased compared to that in the para-tumor area." (PMID 35559019, 2022). "We found that the expression of IGF2BP3 and RBM15B was increased in the glioma area compared to that in the para-tumor area." (PMID 35559019, 2022).
hepatocellular carcinoma (6 papers, 2022 to 2025). A malignant tumor that arises from hepatocytes. "In addition, another study showed that RBM15B was highly expressed in hepatocellular carcinoma, and it promoted hepatocellular carcinoma cell growth, invasion and metastasis in vivo and in vitro, thus resulting in a poor prognosis." (PMID 36003405, 2022). "According to the report, RBM15B enhanced TRAM2 mRNA stability by relying on its m6A methyltransferase activity in the TRAM2 3'‐UTR, thereby promoting hepatocellular carcinoma proliferation." (PMID 40066751, 2025). "RBM15B, the paralog of RBM15, was found involved in prognostic models of several types of tumors, such as alcohol-related hepatocellular carcinoma (A-HCC), small cell lung cancer (SCLC), and melanoma." (PMID 37818090, 2023).
melanoma (5 papers, 2021 to 2023). A malignant, usually aggressive tumor composed of atypical, neoplastic melanocytes. "Coefficients obtained from multivariate Cox analysis were conducted to calculate each melanoma patient’s risk score utilizing the following formula: risk score = (0.675902669) × RBM15B + (0.6078590311) × METTL16 + (0.555973734) × IGF2BP3." (PMID 34446007, 2021). "Temsirolimus and XL-147 exhibited sensitivity for melanoma with RBM15B mutations." (PMID 34446007, 2021). "Next, based on variables of three hub genes (IGF2BP3, METTL16, and RBM15B) expression derived from the all TCGA cohort, a nomogram was constructed to predict the 1-, 2-, and 3-year survival probabilities of melanoma patients." (PMID 34446007, 2021). "The results demonstrated that IGF2BP3 mRNA level was upregulated in melanoma tissues as well, while RBM15B and METTL16 was insignificant, though high expression of RBM15B and METTL16 were associated with poor OS in TCGA database." (PMID 34446007, 2021). "A three-gene prognostic signature including IGF2BP3, RBM15B, and METTL16 was constructed, and the risk score of this signature was identified to be an independent prognostic indicator for melanoma." (PMID 34446007, 2021). "RBM15B has been identified as an independent prognostic indicator of melanoma." (PMID 37074800, 2023). "In addition, antigen processing and presentation, cell cycle, cytokine–cytokine receptor interactions, wnt-signaling, melanogenesis, and other cancer pathways were differentially enriched with high RBM15B expression of melanoma patients." (PMID 34446007, 2021). "Third, the three prognostic panel genes (IGF2BP3, METTL16, and RBM15B) not only influenced the prognosis and clinicopathological features but were also closely correlated with tumorigenesis key signaling pathways, and hallmarks of malignant melanoma." (PMID 34446007, 2021). "Besides, RBM15B and METTL16 in the signature may influence melanoma tumor promotion because they were associated with poor OS in the TCGA database." (PMID 34446007, 2021). "Thirdly, we also preliminary explored novel potential carcinogenic mechanisms of IGF2BP3 with GSEA as well as the role of RBM15B and METTL16 in melanoma, making our study more innovative and colorful." (PMID 34446007, 2021). "Comparing primary melanoma and metastases, we found that ALKBH5, ELAVL1, FMR1, HNRNPA2B1, HNRNPC, IGF2BP1/2/3, KIAA1429, LRPPRC, RBM15, YTHDC1/2, YTHDF1/3, and ZC3H13 were significantly upregulated in metastases, while RBM15B and METTL3 were significantly upregulated in primary melanoma." (PMID 34993195, 2021).
liver cancer (4 papers, 2022 to 2025). An epithelial or non-epithelial malignant neoplasm that arises from the liver. "The expression levels of RBM15 and RBM15B are closely linked to prognosis, immune evasion mechanisms, and resistance to immunotherapy in liver cancer patients." (PMID 39911396, 2025). "Inhibiting the expression of RBM15 and RBM15B has been shown to restore the immune system’s capacity to recognize and effectively target liver cancer cells, thus enhancing the therapeutic efficacy of immune therapies." (PMID 39911396, 2025). "As such, both RBM15 and RBM15B represent promising therapeutic targets for liver cancer immunotherapy." (PMID 39911396, 2025). "Such interventions could provide a novel approach for overcoming resistance to immune checkpoint inhibitors, making RBM15 and RBM15B inhibition a potentially effective strategy to improve liver cancer treatment outcomes." (PMID 39911396, 2025). "Overall, our results showed that the four specific genes, TIPIN, RBM15B, DUSP28, and TRIM31, were likely prognostic biomarkers of liver cancer, and TIPIN might conspicuously accelerate the process of hepatocarcinogenesis." (PMID 35082931, 2022).
pancreatic cancer (4 papers, 2021 to 2023). "ZC3H13 (11%), RBM15B (9%), YTHDF1 (8%), and YTHDC1 (6%) frequently occurred genetic mutations in pancreatic cancer." (PMID 34603372, 2021).
prostate carcinoma (4 papers, 2020 to 2025). A carcinoma that arises from epithelial cells of the prostate gland. "In this study, we found HNRNPA2B1, METTL3, and RBM15B were overexpressed not only in tumor samples but also in high GS prostate cancer patients." (PMID 32710725, 2020). "Moreover, RNA-binding motif protein 15B (RBM15B) enhances prostate cancer cell proliferation by increasing the stability of proliferating cell nuclear antigen (PCNA) mRNA through YTHDF1-induced m6A methylation." (PMID 40986143, 2025). "Currently, there were few pieces of research related to HNRNPA2B1 an RBM15B in prostate cancer." (PMID 32710725, 2020). "The role of HNRNPA2B1, METTL3, and RBM15B may play an oncogene in prostate cancer." (PMID 32710725, 2020). "Seven m6A methylation-related genes (ALKBH5, FMR1, IGFBP3, RBM15B, YTHDF1, YTHDF2, and ZC3H13) were identified as cross-talk genes between prostate cancer and PD." (PMID 36133437, 2022). "However, the expression patterns of the other four genes (ALKBH5, RBM15B, YTHDF1, and YTHDF2) in prostate cancer and periodontitis were not consistent." (PMID 36133437, 2022).
uveal melanoma (4 papers, 2019 to 2025). A melanoma derived from melanocytes of the uveal tract. "Regarding writer genes, analysis of the TCGA database revealed that RBM15B was an independent protective prognostic gene for uveal melanoma." (PMID 41301778, 2025). "Moreover, stage 4 of uveal melanoma had a markedly lower expression level compared with stage 3, indicating that RBM15B inhibit tumor growth and progression." (PMID 36003405, 2022). "The physiological and pathological role of RBM15B in uveal melanoma has been unknown so far." (PMID 36003405, 2022).
breast carcinoma (3 papers, 2019 to 2020). "The high expression of YTHDF3, ZC3H13, LRPPRC, and METTL16 indicated poor survival rate in patients with breast cancer, while high expression of RBM15B pointed to a better survival rate." (PMID 33362863, 2020). "Breast Cancer Gene-Expression Miner v4.5 showed that LRPPRC level was negatively associated with ER and PR expression, while METTL16, RBM15B, ZC3H13 level was positively linked with ER and PR expression." (PMID 33362863, 2020). "BRCA1-associated protein-1 (BAP1) is found to be expressed at a low level in breast cancer patients, while RBM15B has a positive correlation with BAP1 in invasive breast cancer." (PMID 33362863, 2020). "According to the clinical database of breast cancer of TCGA, RBM15B, YTHDF3, ZC3H13, METTL16, and LRPPRC were picked up indicating strong associations with clinical characteristics." (PMID 33362863, 2020). "The results in breast cancer patients showed that the relatively high expression of YTHDF3 and LRPPRC were remarkably associated with worse RFS, whereas relatively high expression of RBM15B, ZC3H13, and METTL16 had better RFS." (PMID 33362863, 2020). "RBM15B expressed higher in Luminal A and normal breast-like subtypes of breast cancer." (PMID 33362863, 2020). "In HER-2 (+) breast cancer patients, LRPPRC, METTL16, RBM15B, and ZC3H13 expressed lower than the HER-2 (−)." (PMID 33362863, 2020). "In the ONCOMINE and TCGA databases, we didn’t notice a considerable difference in the expression of RBM15B and YTHDF3 in breast cancer." (PMID 33362863, 2020). "From another perspective, Kaplan-Meier Plotter platform showed that the relatively high expression of YTHDF3 and LRPPRC and the relatively low expression of RBM15B, ZC3H13, and METTL16 in breast cancer patients had worse Relapse-Free Survival (RFS)." (PMID 33362863, 2020). "In HER-2 (+) breast cancer patients, the expression of LRPPRC, METTL16, RBM15B, and ZC3H13 were all lower than the HER-2 (−) group." (PMID 33362863, 2020). "We discovered that there are three genes (DHX30, USP19, and RBM15B), which are highly positively correlated with BAP1 in both black and white breast cancer patients." (PMID 30716094, 2019). "In this study, we used a series of bioinformatic databases and tools to jointly analyze the expression of m6A methylation transferases (METTL3, METTL14, WTAP, RBM15, RBM15B and ZC3H13) and investigate the prognostic value of METTL14 and ZC3H13 in breast cancer." (PMID 33363011, 2020). "In this study, we used Oncomine and The Cancer Genome Atlas (TCGA) databases to jointly analyze the expression of m6A “writer” in breast cancer including METTL3, METTL14, WTAP, RBM15, RBM15B, and ZC3H13, indicating that the mRNA expression levels of METTL14 and ZC3H13 were lower in tumor samples." (PMID 33363011, 2020). "The expression of METTL3, METTL14, RBM15B, and ZC3H13, but not of WTAP and RBM15, was significantly decreased in breast cancer." (PMID 33363011, 2020). "Furthermore, mining of TIMER database based on TCGA breast cancer samples demonstrated that only the mRNA expression levels of METTL14 and ZC3H13 were also lower in tumor samples, and there was not any difference of METTL3 and RBM15B." (PMID 33363011, 2020).
cervical cancer (3 papers, 2022). A primary or metastatic malignant neoplasm involving the cervix. "PD-L1 expression increased dramatically in cervical cancer tissues and was significantly linked to ALKBH5, FTO, METTL3, RBM15B, YTHDF1, YTHDF3, and ZC3H13 expression levels." (PMID 36091006, 2022).
invasive breast carcinoma (3 papers, 2019 to 2021). A carcinoma that infiltrates the breast parenchyma. "In patients with breast invasive carcinomas, BAP1 is highly positively correlated with NSG00000132153.13 (DHX30), ENSG00000259956.1 (RBM15B), and ENSG00000172046.17 (USP19), in all four categories." (PMID 30716094, 2019). "We found that BAP1 is highly positively correlated with RBM15B and USP19 expression in invasive breast carcinoma, UM, and colon adenocarcinoma." (PMID 30716094, 2019).
osteoarthritis (3 papers, 2022 to 2024). A noninflammatory degenerative joint disease occurring chiefly in older persons, characterized by degeneration of the articular cartilage, hypertrophy of bone at the margins and changes in the synovial membrane. "This showed that infiltrating MDSCs were increased in osteoarthritis, which was closely related to the expression of RBM15B and HNRNPC." (PMID 36777725, 2023). "Among them, VIRMA and LRPPRC were the most highly correlated m6A regulators expressed in all samples and osteoarthritis samples and showed a positive correlation, whereas VIRMA and RBM15B were the most negatively correlated." (PMID 36777725, 2023). "This suggested that RBM15B and HNRNPC played important roles in the natural killer cell response of osteoarthritis." (PMID 36777725, 2023).
asthma (2 papers, 2021 to 2024). "We found that RBM15B was overexpressed in asthmatic patients while the other significant m6A regulators displayed decreased expression in asthma patients compared to non-asthmatic patients." (PMID 33763115, 2021).
colon adenocarcinoma (2 papers, 2019 to 2025). "Another study indicated that glutathione peroxidase 4 (GPX4) activated stimulator of interferon (STING) genes through RBM15B‐mediated m6A modification, thereby promoting an anti‐tumor immune response in colon adenocarcinoma hosts." (PMID 40066751, 2025). "Importantly, USP19 and RBM15B were also among 10 genes with a high positive correlation with BAP1 expression in colon adenocarcinoma." (PMID 30716094, 2019).
ovarian carcinoma (2 papers, 2021 to 2022). A malignant neoplasm originating from the surface ovarian epithelium. "GSEA analysis demonstrated that the expressions of METTL3, YTHDC1, RBM15B, HNRNPC, IGF2BP2, RBMX, and ZC3H13 were correlated with a higher number of multiple Hallmark pathways in ovarian cancer." (PMID 33225598, 2021). "We demonstrated four immune infiltration‐related m6A regulators in ovarian cancer, including RBM15B, ZC3H13, YTHDF1, and IGF2BP1." (PMID 33225598, 2021). "Two GEO databases demonstrated that 7 readers (HNRNPC, IGF2BP1, IGF2BP2, IGF2BP3, RBMX, YTHDC2, and YTHDF2) and 3 writers (METTL3, RBM15, and RBM15B) were more highly expressed in ovarian cancer than in ovarian surface epithelium or normal peritoneum tissues (GEO14407 and GEO12470)." (PMID 33225598, 2021). "Zhang and colleagues, for example, demonstrated that RBM15B was highly expressed in ovarian cancer and increased expression of RBM15B correlated with worse PFS and ovarian cancer cell metastasis." (PMID 36003405, 2022). "Importantly, our data showed that immune cell infiltration levels and various immune gene markers were closely associated with the expression of m6A regulators, suggesting that RBM15B, ZC3H13, YTHDF1, and IGF2BP1 might play the role of immune infiltration‐related m6A regulators in ovarian cancer." (PMID 33225598, 2021).
thyroid cancer (2 papers, 2022). "In particular, HNRNPC, RBM15B, IGFBP2, and ELF3 were upregulated, while the other 12 genes were downregulated in thyroid cancer tissues." (PMID 36389678, 2022). "Most of the key m6A regulators were positively correlated to iodide-handling genes in thyroid cancer, but IGF2BP2, HNRNPC, WTAP, and RBM15B were negatively correlated to iodide-handling genes, and the correlation between IGF2BP2 and iodide-handling gene was the strongest." (PMID 35267576, 2022).
bladder tumors (1 paper, 2021). "However, some m6A regulators, including METTL3, RBM15B, YTHDF1, YTHDF2, and IGFBP3, were significantly overexpressed in bladder tumors, and some m6A regulators, including METTL14, METTL16, ZC3H13, and YTHDF3, were markedly downregulated in bladder tumors." (PMID 35004726, 2021).
COVID-19 (1 paper, 2022). A disease caused by infection with severe acute respiratory syndrome coronavirus 2. "Interestingly, we observed that the expression level of RBM15B was negatively correlated with the patients' risk score, and RBM15B may be a protective factor for COVID-19 patients." (PMID 35655464, 2022). "COVID-19 patients with high expression levels of FTO tend to display high levels of METTL3, METTL16, RBM15B, or VIRMA." (PMID 35655464, 2022). "COVID-19 patients with elevated expression levels of CBLL1, METLL16, and RBM15B presented elevated expression levels of ALKBH5 while elevated METTL14 and ZC3H13 expression demonstrated a negative association with ALKBH5." (PMID 35655464, 2022). "Significant positive correlations were observed between METTL3, METTL16, RBM15B, VIRMA, and FTO in COVID-19 patients." (PMID 35655464, 2022). "We observed that RBM15B, HNRNPA2B1, and VIRMA may be protective factors in the development of COVID-19, and the opposite performance was found in ELAVL1, RBM15, FMR1, IGFBP3, and METTL3." (PMID 35655464, 2022).
dementia (1 paper, 2025). Loss of intellectual abilities interfering with an individual's social and occupational functions. "The KEGG and GO analyses further support the correlations of Rbm15b and Hnrnpa2b1 with post-synaptic modulation in the development of AD related dementias." (PMID 40666518, 2025).
depression (1 paper, 2022). "Next, we performed differential gene analysis of m6A regulators in depression and found that FTO, RBM15B, METTL3, LRPPRC, HNRNPC, ZC3H13, and YTHDF2 were significantly upregulated in depressed rats." (PMID 35480327, 2022).